CDK2 (cyclin dependent kinase 2)
Diseases named in the same sentence as CDK2 in open-access papers (continued):
Sharing a sentence is not in itself a finding about the gene and the disease.
osteosarcoma (continued). "Another most interesting observation in our study is that a few of the hub genes of Rb tumors including CDK1, CDK2, CCNB1, HDAC1 and UNC5D are reported to play a key role in the pathogenesis of osteosarcoma, the most common secondary cancer in Rb patients." (PMID 35359459, 2022). "Previous studies have also shown that inhibition of CDK2/9 in triple-negative BC cells and CDK9 inhibition in osteosarcoma cells decreased migration by preventing phosphorylation of CDK-mediated Smad3 and RNA POL-ll in triple-negative BC33,34." (PMID 33723248, 2021). "Colony formation and CCK8 assays revealed that BMS-794833 inhibited the proliferation of osteosarcoma cells in the shNC group; however, these inhibitory effects were not significant in the sh-CDK2 group." (PMID 38532893, 2024). "BAMBI has also been reported to regulate cyclin D1, CDK2, and CDK6 in human osteosarcoma cells." (PMID 36109807, 2022). "In addition, silencing of RTKN2 of human osteosarcoma cell lines U2OS, inhibited proliferation, and induced G1 phase cell cycle arrest via reducing the level of the cyclin-dependent kinase 2 (CDK2)." (PMID 30389712, 2018). "We also observed a significant decrease in CDK2 levels after down-regulation of CUL4B, DDB1 or DCAF11 in osteosarcoma cells, which raised the question of whether DCAF11 is responsible for the degradation of CDK2." (PMID 28446751, 2017). "Thus, CDK2 might be only a CUL4B-associated protein, and its down-regulation in osteosarcoma cells expressing lower CUL4B, DDB1 or DCAF11 might not be regulated by DCAF11 but might rather be regulated by p21 induction, as p21 is an inhibitor of CDK2." (PMID 28446751, 2017).
lung adenocarcinoma (17 papers, 2015 to 2025). A carcinoma that arises from the lung and is characterized by the presence of malignant glandular epithelial cells. "The loss of CDK2 in lung adenocarcinoma cell lines cannot dramatically suppress the tumor growth, indicating that CDK2‐mediated DRP1 activation is dispensable for proliferation." (PMID 33152171, 2021). "Additionally, CDK2 expression is strongly associated with immune responses in cancer and prognostic value in lung adenocarcinoma." (PMID 40088196, 2025). "For example, β-sitosterol induces cell cycle arrest in lung adenocarcinoma by blocking Cyclin-D1 and cyclin-dependent kinase 2 (CDK-2)." (PMID 39065711, 2024). "Our data further revealed that DRP1 activation through serine 616 phosphorylation is regulated by ERK/AKT and CDK2 in lung adenocarcinoma cell lines." (PMID 33152171, 2021). "Here, we demonstrated that the multikinase framework including ERK/AKT and CDK2 promotes the proliferation and invasion of lung adenocarcinoma cell lines through activating DRP1." (PMID 33152171, 2021). "We confirmed the specific role of CDK2 in regulating mitotic mitochondrial fission in lung adenocarcinoma cell lines." (PMID 33152171, 2021). "Forced over-expression of miR-186 in lung adenocarcinoma cells inhibits proliferation and invasion by targeting and inhibiting the cyclin D1, cyclin-dependent kinase 2 (CDK2), and CDK6 genes and pituitary tumor transforming gene." (PMID 25742499, 2015). "Interestingly, using lung adenocarcinoma cell lines including A549, HOP62, and H23, we observed an increased expression of cdk2, 4, and 6 following the loss of either UBQLN1 or UBQLN2." (PMID 37444499, 2023). "Furthermore, cell cycle analysis showed miR-363-3p can induce S phase arrest by downregulating Cyclin-D1 and upregulating Cyclin-dependent kinase-2 in lung adenocarcinoma cells." (PMID 28423618, 2017). "Interestingly, depleting CDK2 in lung adenocarcinoma cell lines resulted in similar mitochondrial morphological changes caused by DRP1 depletion and led to an extensive mitochondrial tubular network in CL1‐0 cells and perinuclear compaction of swollen mitochondria in A549 cells." (PMID 33152171, 2021). "Additionally, our findings suggested that combination treatments to inhibit ERK/AKT and CDK2 may potentially be effective in lung adenocarcinoma through perturbing mitochondrial dynamics, and further investigations are warranted." (PMID 33152171, 2021). "Since other kinases, such as ERK and AKT, can regulate the activation of DRP1 in lung adenocarcinoma cell lines, the GTPase activity of DRP1 can thus be maintained even though CDK2 is depleted." (PMID 33152171, 2021). "In conclusion, we present the functional role of DRP1 in enhancing the proliferation and invasiveness of lung adenocarcinoma cell lines and further show that multikinase regulatory molecules, including ERK, AKT, and CDK2, secure the activation of DRP1." (PMID 33152171, 2021). "We show that YTHDF1 deficiency inhibits NSCLC cell proliferation and xenograft tumor formation through regulating the translational efficiency of CDK2, CDK4, and cyclin D1, and that YTHDF1 depletion restrains de novo lung adenocarcinomas (ADC) progression." (PMID 31653849, 2019). "We have previous results showed that YTHDF1 promotes NSCLC cell proliferation and xenograft tumor formation by mediating the translational efficiency of cyclin D1, cyclin-dependent kinase 2 (CDK2), and CDK4, and that YTHDF1 elimination inhibits de novo lung adenocarcinoma (ADC) progression." (PMID 36650570, 2023). "Based on the activity of these CDK inhibitors, we speculated that CDK2, CDK4/6, and CDK5 are candidates that activate DRP1 during the cell cycle in lung adenocarcinoma cell lines." (PMID 33152171, 2021). "Although CDK4/6 might compensate for CDK2 in regulating cell cycle progression, our data revealed that CDK4/6 is not crucial for mitosis‐related mitochondrial fragmentation in lung adenocarcinoma cell lines." (PMID 33152171, 2021).
multiple myeloma (17 papers, 2015 to 2025). "Our results demonstrate that APG treatment significantly downregulated Cyclin D1 and CDK2 expression while upregulating P21 in multiple myeloma (MM) cells." (PMID 41020839, 2025). "In this study, treatment of myeloma cells with DCZ0801 down-regulates the level of CDK2, Cyclin A2, and CDC 25A, which arrests the cell cycle in the S phase." (PMID 32626538, 2020). "Multiple Myeloma: Incubation of various multiple myeloma cell lines with seliciclib, a selective CDK2/E, CDK2/A, CDK7 and CDK9-inhibitor, resulted in apoptosis." (PMID 32380689, 2020). "Dinaciclib, identified as a candidate drug in the 4,560-drug screen, was also investigated because the Cdk (Cdk1, 2, 5, 9, and 12) inhibitor dinaciclib was reported as an encouraging single agent in multiple myeloma, and the Cdk2/9 inhibitor showed efficacy in CCC organoids." (PMID 40459063, 2025). "For example, TRIM21 is involved in degradation of cyclin-dependent kinase 2 (CDK2) and ATG5 in AML and multiple myeloma cells." (PMID 40371639, 2025). "Collectively, these findings suggest that UNC13B may regulate multiple oncogenic and apoptotic signaling pathways—such as those involving PINK1, CDK2, AKR7A3, and Bim—to promote cell survival and proliferation in multiple myeloma." (PMID 41007649, 2025).
renal cell carcinoma (16 papers, 2014 to 2025). "Further studies revealed that WTAP enhanced cyclin dependent kinase 2 (CDK2) mRNA stability by directly targeting to the 3′-UTR of CDK2 transcript, thus upregulating CDK2 expression and promoting the proliferation of renal cell carcinoma cells." (PMID 36139062, 2022). "WTAP regulates CDK2 mRNA stability, which is related to the G1/S transition, in renal cell carcinoma (RCC) and keratinocytes." (PMID 36207306, 2022). "Silencing of tumor susceptibility 101 reduced proliferation and induced G0/G1 arrest by markedly decreasing the expression of cyclin E1/CDK2 in renal cell carcinoma." (PMID 35246013, 2022). "p21Cdkn1a mediates G1 arrest by inhibiting CDK1 and CDK2 and loss of CDKN1A is a predictor of poor outcome in renal cell carcinoma." (PMID 35401501, 2022). "WTAP promotes renal cell carcinoma proliferation by regulating CDK2 mRNA stability." (PMID 35761192, 2022). "Besides, WTAP promotes renal cell carcinoma proliferation by regulating CDK2 mRNA stability." (PMID 39744575, 2025). "In renal cell carcinoma (RCC), WTAP promoted the mRNA stability of Cdk2, a regulator of cell cycle control over the G1/S and S/G2 transition, by directly binding to the Cdk2 transcript at the 3′-UTR." (PMID 35350378, 2022).
breast tumors (14 papers, 2009 to 2025). "In our previous GSEA analysis of 836 primary breast tumor transcription profiles, we identified NF-κB pathway to be associated with positive lymph node status of luminal A patients in general and linked Cdk2 to the high risk of distant metastasis in lymph node negative luminal A patients." (PMID 37620794, 2023). "CDK2 is upregulated in breast tumors, and its vital role in cell cycle regulation makes CDK2 an attractive therapeutic target." (PMID 36003501, 2022). "CDK2 gene expression was also higher in basal-like subtype compared with the less aggressive LumA or normal-like breast tumors." (PMID 35884422, 2022). "It has been demonstrated by Western blot and by immunoprecipitation that breast tumor cell lines treated in vitro with trastuzumab increased p27kip1 levels and interaction with CDK2, resulting in a decrease in CDK2 activity." (PMID 22295219, 2011). "CDK2 specific activity in breast tumors would therefore be another indicator of paclitaxel sensitivity." (PMID 19239702, 2009). "We next measured the specific activities of CDK1 and CDK2 in breast tumors resected from mice 24 hours after a single dose of paclitaxel." (PMID 19239702, 2009). "In addition, DDX5 and ZC3H12D were also positively and negatively correlated with the expression of several cell cycle‐promoting genes, such as WEE1 and CDK2, in human breast tumor tissues." (PMID 41263459, 2025). "They suggested that the use of CDK2 inhibitors in patients with breast tumors with HER2 and cyclin E coamplification/overexpression might be a valid strategy." (PMID 22295219, 2011). "While CDK4/6 inhibitors like Palbociclib in combination with TAM may potentially arrest the in vivo growth of ERmut expressing breast tumors, CDK2 inhibitors like Dinaciclib when given in combination with TAM may be more effective by inducing regressions in established ERmut expressing tumors." (PMID 29137354, 2017). "In contrast to normal human epithelial cells, HR‐positive breast tumors proliferate via autocrine mechanisms that involve PR‐induced expression of RANKL, Wnt4, and cyclin D1, as well as PR‐induced activation of protein kinases including CDK2, c‐Src, CK2, MAPK, and PI3K/AKT." (PMID 34714554, 2022). "As the authors of both studies study point out, inhibition of CDK2 is of paramount importance for the induction of cell cycle arrest in breast tumor cells that respond to CDK4/6 inhibitors and without CDK2 inhibition, patients will undoubtedly develop resistance to this class of therapeutics." (PMID 36051751, 2022).
viral infection (10 papers, 2013 to 2026). "In the investigation that followed, core targets were HSP90AA and CDK2, which were proven to be linked to viral infection." (PMID 36034788, 2022). "Our findings demonstrated that the survival rate under viral infection was significantly higher in the cdk2-/- group than in the wild-type group." (PMID 41532831, 2026). "During the 48 hr (h) viral infection period, CDK2 was significantly upregulated at the protein level." (PMID 41532831, 2026). "Altogether, our findings expand the understanding of mechanisms underlying HCMV-induced cell cycle dysregulation and point toward regulatory feedback between SIRT2 and CDK2 that can have implications in other viral infections and human diseases." (PMID 37916830, 2023). "CDK2 reportedly plays a role in phosphorylating HBV capsids to trigger nucleocapsid disassembly during viral infection." (PMID 36034788, 2022). "The transcripts remain unchanged, upon viral infection, at 3 and 24 hrs and only at 9 h p.i. we noted a decrease of CDK2 transcripts levels." (PMID 28835716, 2017). "We also evaluated the effects of CDK2 on the cellular protein production in response to viral infection." (PMID 23437375, 2013). "The level of cellular proteins in response to viral infection altered by CDK2 inhibition was also examined in WI-38 cells." (PMID 23437375, 2013). "However, the precise upstream signaling pathways that regulate CDK2 during viral infection remain to be fully elucidated." (PMID 41532831, 2026). "Moreover, gene set enrichment analyses (GSEAs) were performed to analyze the IFN response to virus infection-related genes, which demonstrated that these genes were significantly activated in the cdk2-/- group." (PMID 41532831, 2026). "Taken together, the in vivo and in vitro data suggest that fish CDK2 may play a role in the response to viral infection." (PMID 41532831, 2026). "The CDK2 protein level was also consistently higher in the viral infection group." (PMID 41532831, 2026). "The impact of CDK2 on viral infection was examined in relation to IFN." (PMID 41532831, 2026). "It is possible that CDK2 could be transported into the nucleus in a “piggyback” manner, interacting with a viral protein that shuttles between nucleus and cytoplasm, or that viral infection activates the intrinsic CDK2 import machinery." (PMID 30510918, 2018). "In support of our notion, mass spectrometry analysis revealed that S130 in p21 is indeed phosphorylated in mitotic HeLa cells, although this residue is also phosphorylated by Cdk2/cyclin E in the S phase, Cdk6/cyclin K upon viral infection and ERK2 after mitogenic stimuli." (PMID 27384476, 2016). "In previous studies, it was found that mammalian cdk2 was not regulated during viral infection." (PMID 41532831, 2026).
retinoblastoma (9 papers, 2014 to 2025). A malignant tumor that originates in the nuclear layer of the retina. "CDK2 being a protein known to cause tumour penetrance in all retinoblastoma models, removal of p107 in an Rb knockout model causing activation of CDK2 and post transcriptional induction of S-phase kinase-associated protein 2 (SKP2) further established the crosstalk among these proteins." (PMID 37667345, 2023). "HDAC9 expression is associated with cell proliferation in vitro, and its inhibition with cell arrest in the G1 phase is consistent with the reduction of Cyclin E2 and CDK2 expression in retinoblastoma cells." (PMID 37887350, 2023). "Inactivating this CDK2 inhibitor or deleting p27 expression was thus found to induce retinoblastoma." (PMID 37667345, 2023). "In summary, we demonstrated that TAZ promotes retinoblastoma growth via downregulating Cyclin E and CDK2 expression." (PMID 26464030, 2015). "Activity of Cdk2/Cyclin E is essential for phosphorylation of Retinoblastoma and release of E2F1." (PMID 34520549, 2021). "Interestingly, the most potent compound was able to selectively inhibit CDK2-mediated Retinoblastoma phosphorylation, confirming that its mechanism of action is fully compatible with a selective inhibition of CDK2 phosphorylation in cells." (PMID 31355188, 2019). "Specifically, p27 inhibits CDK2 and CDK4/6 thereby preventing the phosphorylation of the Retinoblastoma." (PMID 41009443, 2025). "We found that the expression of Cyclin E and CDK2 was downregulated in retinoblastoma cells with TAZ knockdown, but no obvious changes were observed in Cyclin D1, CDK4 and CDK6 expression." (PMID 26464030, 2015).
sarcoma (9 papers, 2009 to 2026). A usually aggressive malignant neoplasm of the soft tissue or bone. "We anticipate that this conserved CCNE/CDK2-POLE-WEE1 axis will serve as a molecular network to therapeutically exploit to improve outcomes for patients with CIC::DUX4 sarcoma." (PMID 40760094, 2025). "Although cyclin-dependent kinase inhibitor p16 was highly expressed in both sarcomas, another CDK inhibitor p21 showed significantly lower expression and cell cycle accelerators including CDK2 and 4, cyclinD1 and E1 were highly expressed in both sarcomas." (PMID 22852096, 2012). "Moreover, through analysis of TCGA, we found that sarcoma patients with low expression of CDK2 had higher enrichment scores of T cells, DC, NK cells, macrophages and neutrophils." (PMID 40557162, 2025). "In addition, considering the dependence of CIC-DUX4 sarcoma on the CCNE-CDK2 cell cycle complex, the effects of pharmacological inhibition of CDK2, a CCNE1 binding partner, were investigated in CIC-DUX4 cells." (PMID 36358827, 2022). "Downregulation of p21Cip1 and higher expression of CDK4-cyclinD1 and CDK2-cyclinE could accelerate cell cycle in sarcomas." (PMID 22852096, 2012). "To this end, we recently observed that CIC-DUX4 sarcoma is molecularly dependent on the CCNE/CDK2 complex: CIC-DUX4 acquires neomorphic function as a transcriptional activator to upregulate CCNE1, driving sarcoma growth and survival." (PMID 35315355, 2022).
head and neck cancer (8 papers, 2012 to 2023). A primary or metastatic malignant neoplasm affecting the head and neck. "Accordingly, we found that the expression of both Cdk1 and Cdk2 was inhibited by esomeprazole in HN30 head and neck cancer cells." (PMID 34262645, 2021). "In head and neck cancer, CDK2AP1 inhibits CDK2/CyclinE activity, while under normal conditions CDK2/CyclinE can phosphorylate Retinoblastoma Protein (Rb), release E2F, and then transcribe the required components of the cell, subsequently going through the G1/S phase transition." (PMID 36105112, 2022).
HIV-1 infection (8 papers, 2009 to 2025). The type species of lentivirus and the etiologic agent of acquired immunodeficiency syndrome (AIDS). "RT-qPCR analysis of PBMCs showed that both HEAL and CDK2 mRNA expression was upregulated by HIV-1 infection, consistent with the findings in H9 and MT4 T cell lines." (PMID 31551335, 2019). "The CDK2 KD inhibited HIV-1 replication in agreement with our recent report showing reduction of one round HIV-1 infection in CDK2 KD cells." (PMID 29792216, 2018). "Iron and oxygen availability have been reported to affect HIV-1 infection in a number of studies, implicating several potential mechanisms including cell cycle effects mediated by factors such as eIF5A and CDK2." (PMID 24086341, 2013). "The CCNE2, as the substrate of CDC4 was reported to act as a dependency factor to induce HIV Tat activity by encoding protein Cyclin E1, Cdk2 and Cyclin E. It is speculated that HIV-1 hijacks CDC4 to sequester it to prevent the degradation of CCNE2, facilitating HIV-1 infection in the target cells." (PMID 40260685, 2025). "Thus, p21 may restrict HIV-1 infection through anti-CDK2/9 properties and CDK2 phosphorylation effects of HIV-1 Tat may enhance HIV-1 infection." (PMID 32326317, 2020). "Peptide analogs of Tat have been shown to inhibit Tat's ability to recruit cdk2 to the LTR, and to decrease transcription in vitro and viral load in a small animal model of HIV-1 infection." (PMID 20030845, 2009). "Inhibitors of CHEK2, CSNK2A1, and CDK2 did not significantly reduce CCR5-tropic HIV-1 infection but inhibited CXCR4-tropic HIV-1 at one or more concentrations." (PMID 29970186, 2018). "Our recent study showed that CDK2 activity was inhibited in peripheral blood mononuclear cells obtained from patients with sickle cell disease, which led to the activation of SAMHD1 and inhibition of ex vivo HIV-1 infection." (PMID 29792216, 2018).